NLRP3 (NLR family pyrin domain containing 3)
Diseases named in the same sentence as NLRP3 in open-access papers (continued):
Sharing a sentence is not in itself a finding about the gene and the disease.
Salmonella Infections (36 papers, 2013 to 2025). Infections with bacteria of the genus SALMONELLA. "In ilea, Salmonella infection caused damage-induced intestinal cell death and NLRP3 activation in the present study." (PMID 35163196, 2022). "NLRP3 is known to be associated with NLRC4 during Salmonella infection and regulate inflammasome activation." (PMID 30062052, 2018). "This discrepancy probably leads to the susceptibility of NLRP3 in response to Salmonella infection." (PMID 33384666, 2020). "In addition, genetic ablation of both NLRC4 and NLRP3 in mice leads to increased susceptibility to Salmonella infection." (PMID 32723297, 2020). "Therefore, the present research aimed to investigate the effectiveness of postbiotics from Lactiplantibacillus plantarum (formerly known as Lactobacillus plantarum) on protecting mice against Salmonella infection and elucidate the underlying mechanisms modulating NLRP3 inflammasome and autophagy." (PMID 37893938, 2023). "Subsequent mechanistic studies further revealed that NLRC4 and NLRP3 are physically recruited together into a single macromolecular inflammasome complex during Salmonella infection." (PMID 41062723, 2025). "The NLRP3 protein is highly activated in Salmonella infection, although the uORF-mediated translational regulation of Nlrp3 is currently unclear." (PMID 41188240, 2025). "Earlier investigations into inflammasome signaling revealed that NLRC4 and NLRP3 have overlapping and cooperative functions in the host defense against Salmonella infection." (PMID 41062723, 2025). "Human macrophages undergo NAIP/NLRC4- and NLRP3-dependent inflammasome activation during Salmonella infection, which restricts intracellular Salmonella replication." (PMID 40162563, 2025). "In this study, we found that postbiotics derived from Lactiplantibacillus plantarum significantly alleviated Salmonella infection by inhibiting bacterial pathogenicity and modulating autophagy and NLRP3 inflammasome in mice." (PMID 37893938, 2023). "Salmonella infection can trigger the activation of NLRP3 and NLRC4 inflammasomes which are subsequently involved in pyroptosis and the clearance of bacteria in vivo." (PMID 37155697, 2023). "In the context of Salmonella infection, it has also been reported that CARD9 negatively regulates IL-1β by fine-tuning pro-IL-1β expression, SYK-mediated NLRP3 activation and repressing inflammasome-associated caspase-8 activity." (PMID 37528097, 2023). "Salmonella infection promotes the expression of inflammasome NLRP3, leading to activation and release of proinflammatory cytokines such as IL-1β, and the infected host often displays altered nutrient levels." (PMID 36704315, 2023). "In conclusion, LP postbiotics suppressed Salmonella infection via inhibiting bacterial pathogenicity and modulating autophagy and NLRP3 inflammasome in mice." (PMID 37893938, 2023). "In summary, Lactiplantibacillus plantarum-derived postbiotics alleviated Salmonella infection via modulating bacterial pathogenicity, autophagy and NLRP3 inflammasome in mice." (PMID 37893938, 2023). "Salmonella infection causes disruption of glycolysis, leading to a decrease in NAD+/NADH, which activates NLRP3 inflammasome." (PMID 36814903, 2023). "In mice, the NAIP/NLRC4 inflammasome is important for controlling Salmonella replication in the intestine, whereas the NLRP3 inflammasome is dispensable for control of Salmonella infection in vivo." (PMID 35073381, 2022). "We observed NLRP3 activation induced by Salmonella infection that is likely due to activity of the SPI-1 T3SS, since we do not observe inflammasome activation when we infect THP-1 macrophages with ΔsipB." (PMID 35073381, 2022). "In mice, in addition to the NAIP/NLRC4 and NLRP3 inflammasomes, Salmonella infection can also activate the caspase-11 inflammasome." (PMID 35073381, 2022). "Recently, both the NAIP/NLRC4 and NLRP3 (NLR pyrin domain-containing protein 3) inflammasomes have been shown to respond to Salmonella infection in human macrophages." (PMID 35073381, 2022).
Salmonella Infections (continued). "NLRC4 and NLRP3 inflammasomes can detect exogenous and endogenous molecules that serve as indicators of Salmonella infection." (PMID 32723297, 2020). "Inflammasomes play a key and multilayered role at distinct stages of immune defense against Salmonella infection, although unexpected redundancy was found among NLRP3 and NLRC4 in vivo." (PMID 32723297, 2020). "In that line, Salmonella infection has recently been shown to induce recruitment of both NLRP3 and NLRC4 to the same inflammasome complex along with ASC, caspase-1, and caspase-8." (PMID 28403163, 2017). "In this work, we tried to further detail the role of key-inflammasome proteins ASC and NLRP3 during in vivo Salmonella infection." (PMID 25115174, 2014). "In the present study we aimed to characterize the in vivo relevance of the central inflammasome molecules ASC and NLRP3 in two different murine models of systemic Salmonella infection." (PMID 25115174, 2014). "In order to study the in vivo role of ASC and NLRP3 in invasive salmonellosis, we used a murine typhoid model for severe Salmonella infection." (PMID 25115174, 2014). "In this study, we examined the in vivo relevance of ASC and NLRP3 during Salmonella infection using two clinically relevant experimental models." (PMID 25115174, 2014). "Similar to NLRP3 -/- mice, lncOlfr29 -/- mice had also reduced resistant to Salmonella infection." (PMID 40933997, 2025). "Previous studies showed that NLRP3 played an important role to Salmonella infection." (PMID 40933997, 2025). "It is known that Salmonella infection induces the expression of inflammasomes such as NLRP3 (nucleotide-binding, oligomerization domain- (NOD-) like receptor family, pyrin domain containing 3) to release proinflammatory cytokines like IL-1β (interleukin 1 beta)." (PMID 36704315, 2023). "NLRP3 has been shown to be important in Salmonella infection when the SPI-I activity is low." (PMID 34864057, 2022). "Therefore, Salmonella infection disrupts host cell metabolism, which in turn triggers activation of the NLRP3 inflammasome." (PMID 35630356, 2022). "Therefore, similar to NLRP3, lncOlfr29 promotes resistance to Salmonella infection." (PMID 40933997, 2025). "Mice lacking both NLRC4 and NLRP3 are significantly more susceptible to Salmonella infection." (PMID 37155697, 2023). "Therefore, triggering autophagy to inhibit NLRP3 inflammasome may be essential to control inflammatory responses during Salmonella infection." (PMID 37893938, 2023). "While the precise nature of this interaction is still a subject of debate, it has been suggested that the NAIP/NLRC4/ASC complex formed after Salmonella infection may recruit NLRP3, potentially amplifying caspase-1 cleavage and subsequent IL-1β cytokine release." (PMID 38124741, 2023). "Similar to NLRC4, deficiency in only NLRP3 does not lead to differences in Salmonella infection." (PMID 24381573, 2013). "In human THP-1s, Salmonella infection triggers recruitment of both NLRC4 and NLRP3 to the same macromolecular complex, and the NAIP and NLRP3 inflammasomes both contribute to inflammasome responses to Salmonella." (PMID 35073381, 2022). "A recent study, which also found that Salmonella infection induces NLRC4- and NLRP3-dependent inflammasome activation in human macrophages, observed that full-length Salmonella flagellin can activate the NLRP3 inflammasome." (PMID 35073381, 2022). "Salmonella infection induces NAIP/NLRC4-, CASP4/5-, and NLRP3-dependent inflammasome activation in human macrophages." (PMID 35073381, 2022). "Altogether, these data indicate that Salmonella infection induces both NAIP/NLRC4- and NLRP3-dependent inflammasome activation in human macrophages, in agreement with previous studies." (PMID 35073381, 2022). "In contrast, Salmonella infection induced activation of inflammasome responses that depended on the collective responses of NAIP/NLRC4, NLRP3, and CASP4/5." (PMID 35073381, 2022).
Salmonella Infections (continued). "There had been an interaction between heat stress and Salmonella infection in the expressions of TNF-α, IL-6, IL-1β, pro-IL-1β, and NLRP3." (PMID 34061266, 2021). "Although the roles of NLRP3 and NLRC4 in intestinal immune defense against S. Typhimurium invasion have been studied, their precise functions of spvC-mediated Salmonella infection in the gut remain elusive." (PMID 33384666, 2020). "Our findings are in lines with previous reports about NLRC4 and NLRP3 co-localization into a unique complex in HEK293 cells and in mice bone marrow-derived macrophages during Salmonella infection." (PMID 31244842, 2019). "In contrast to NLRC4 and NLRP3, NLRP6 and NLRP12 negatively regulate the inflammatory responses during Salmonella infections." (PMID 29594070, 2018). "Previous studies showed that NLRP3 and NLRC4 recruit ASC and caspase-1 in response to bacterial trigger, and both of NLRC4 and NLRP3 are activated during Salmonella infections." (PMID 29594070, 2018). "From the previous studies, which were performed in the typhoid model of Salmonella infection, we concluded that ASC and NLRP3 only play a very limited role in the systemic immune response to S. Typhimurium infection." (PMID 25115174, 2014). "Other investigators also showed that caspase-4/11 in intestine epithelial cells could act independently of NLRP3 to directly process IL18 and induce pyroptosis during Salmonella infection." (PMID 36436756, 2023). "In murine macrophages, Salmonella infection activates both the NAIP/NLRC4 and NLRP3 inflammasomes." (PMID 35073381, 2022). "Overall, these data indicate that Salmonella infection of human macrophages triggers activation of multiple inflammasomes, and at least two of these inflammasomes, the NAIP/NLRC4, and the NLRP3 inflammasomes, appear to be essential for controlling bacterial replication within macrophages." (PMID 35073381, 2022). "Therefore, the role of NLRP3 and NLRC4 regulated by spvC to drive cell fate decisions between autophagy and pytoptosis in Salmonella infection deserves further investigation." (PMID 34335562, 2021). "It is widely reported that NLRP3 and NLRC4 inflammasomes are activated during Salmonella infection." (PMID 32723297, 2020). "Treatment with general DUB inhibitors (such as PR-619 and WP1130) has a negative effect on LPS/ATP-induced deubiquitination of NLRP3 and it also inhibits caspase-1 activation during Salmonella infection, which suggests that DUBs are involved in this process." (PMID 26267804, 2015). "However, deletion of both NLRC4 and NLRP3 recapitulates the Caspase-1 phenotype completely, confirming a role for both NLRC4 and NLRP3 during Salmonella infection." (PMID 24381573, 2013). "However, studies of human IECs found that NLRP3 does not play a role in inflammasome activation in response to Salmonella infection, potentially due to very low levels of NLRP3 expression in human IECs as compared to human macrophages." (PMID 37615436, 2023). "However, it remains unknown how NLRP3 and CASP4/5 inflammasomes are activated in human macrophages during Salmonella infection." (PMID 35073381, 2022). "The results showed that GlcN not only inhibited NLRP3 inflammasome but also reduced IL-1β secretion in AIM2-, non-canonical- and NLRC4-inflammasome activated J774A.1 macrophages, which are stimulated by poly(dA:dT) and LPS transfection or by Salmonella infection, respectively." (PMID 30944389, 2019).
oral squamous cell carcinoma (35 papers, 2017 to 2025). "In patients with oral squamous cell carcinoma, 5-FU application increases expression and activation of NLRP3 that is associated with higher tumor stage, moderate/poor differentiation, and poor prognosis." (PMID 36932407, 2023). "Some studies have observed significantly high expression of NLRP3 in paraffin-embedded oral squamous cell carcinoma tissues, which was associated with lymph nodes, tumor size, and metastatic status." (PMID 34393801, 2021). "Furthermore, it has been reported that high NLRP3 expression is associated with poor clinical outcome in 5-FU-treated oral squamous cell carcinoma (OSCC) patients and NLRP3 knockdown increased 5-FU-induced apoptosis in OSCC cells." (PMID 33602906, 2021). "Furthermore, in glioblastoma and oral squamous cell carcinoma, NLRP3 inflammasomes are associated with chemoradioresistance." (PMID 30447690, 2018). "For example, overexpression of NLRP3 is found in oral squamous cell carcinoma, leading to resistance to 5-fluorouracil (5-FU)." (PMID 41278192, 2025). "Melatonin inhibits the development of oral squamous cell carcinoma by interrupting the MIF/NLRP3/IL-1β signaling pathway promoted by macrophages." (PMID 40756978, 2025). "In human oral squamous cell carcinoma, NLRP3 is overexpressed compared to normal oral mucosal epithelial cells and is correlated with the tumor size and lymphatic node metastatic status." (PMID 38523155, 2024). "Anthocyanin activates pyroptosis in oral squamous cell carcinoma cells via enhancing the expression of NLRP3, caspase-1, and IL-1β." (PMID 36932407, 2023). "Increased NLRP3 is positively correlated with the growth and metastasis of oral squamous cell carcinoma (OSCC)." (PMID 36457716, 2022). "NLRP3 activation in cancer has been attributed to response to chemotherapy in triple-negative breast cancer and oral squamous cell carcinoma." (PMID 35631400, 2022). "For instance, the NLRP3 inflammasome is activated by 5-fluorouracil (5-FU) in oral squamous cell carcinoma (OSCC) cells, and mediates chemoresistance by inhibiting apoptosis via ROS/IL-1β upregulation." (PMID 32209729, 2020). "The present study was designed to investigate the expression and function of the NLR family pyrin domain containing protein 3 (NLRP3) inflammasome in oral squamous cell carcinoma (OSCC)." (PMID 29716544, 2018). "In this study, we explored the role of NLRP3 inflammasome in 5-FU resistance of oral squamous cell carcinoma (OSCC)." (PMID 28637493, 2017). "These PDEVs could inhibit distant metastasis of oral squamous cell carcinoma by downregulating NLRP3 expression." (PMID 41278192, 2025). "In oral squamous cell carcinoma cells, anthocyanin could reduce the viability, inhibit the migration and invasion abilities and enhance the expression of NLRP3, caspase-1 and IL-1β." (PMID 39616223, 2024). "High expression of NLRP3 is also associated with the growth, invasion, and metastasis of HNSCC, with poor clinical prognosis in patients with oral squamous cell carcinoma (OSCC) treated with 5-FU, and NLRP3 gene knockout increases pyroptosis of 5-FU-induced OSCC cells." (PMID 36600313, 2023). "Increased expression of NLRP3 enhances the 5-FU resistance of oral squamous cell carcinoma (OSCC)." (PMID 36457716, 2022). "Moreover, the NLRP3 inflammasome is involved in chemoresistance in oral squamous cell carcinoma and insensitivity to radiotherapy in glioblastoma." (PMID 34298833, 2021). "Moreover, the authors found that overexpression of the NLRP3 protein contributed to the malignant biological behaviors of oral squamous cell carcinoma." (PMID 34393801, 2021). "However, 5-FU-mediated NOD-like receptor family pyrin domain containing 3 (NLRP3) inflammation activation induced the resistance of oral squamous cell carcinoma (OSCC) cells to 5-FU." (PMID 34454534, 2021). "Researchers unveiled that NLRP3 stimulation could mediate the resistance to 5-Fluorouracil both in vitro and in vivo in oral squamous cell carcinoma." (PMID 32578856, 2020).
oral squamous cell carcinoma (continued). "Moreover, 5-Fluorouracil (5-FU)-based clinical chemotherapy increased the expression and activation of NLRP3 inflammasome in oral squamous cell carcinoma (OSCC) tissues, which then mediated the chemoresistance." (PMID 32577124, 2020). "In oral squamous cell carcinoma, NLRP3 can accelerate tumor growth and metastasis, and many factors including K+ efflux, intracellular calcium, endoplasmic reticulum (ER) stress, and ROS can activate the NLRP3 inflammasome, including bitter melon-derived PDEVs." (PMID 41278192, 2025). "In addition, it was proved that NLRP3 inflammasome could promote resistance of 5-fluorouracil to oral squamous cell carcinoma." (PMID 37304662, 2023). "In oral squamous cell carcinoma (OSCC), current evidence points to a predominantly pro-tumorigenic role, with elevated NLRP3 expression correlating with tumor progression, lymph node metastasis, advanced pathological stage, and reduced survival." (PMID 41560727, 2025). "In the context of oral squamous cell carcinoma (OSCC), accumulating evidence indicates that NLRP3 predominantly exerts a pro-tumorigenic function." (PMID 41560727, 2025). "NLRP3 was correlated with the tumor growth and metastasis of oral squamous cell carcinoma (OSCC), and knockdown of NLRP3 significantly inhibited the proliferation, migration and invasion of OSCC cells." (PMID 37064086, 2023). "Interestingly, the levels of the NLRP3 complex components (NLRP3, ASC and IL-1β) were significantly elevated in oral cavity squamous cell carcinoma (OSCC) and contributed to tumor growth and metastasis." (PMID 34064909, 2021). "Similarly, NLRP3 expression levels are also correlated with the tumor size, lymph node metastatic status and IL-1β expression in oral squamous cell carcinoma (OSCC), and downregulating NLRP3 expression markedly attenuates the proliferation, migration, and invasion of OSCC." (PMID 33613533, 2020).